SAA1 (serum amyloid A1)
Diseases named in the same sentence as SAA1 in open-access papers (continued):
Sharing a sentence is not in itself a finding about the gene and the disease.
breast cancer (continued). "The results of this study show that the absence of SAA1/2 isoforms in SAADKO mice does not significantly affect overall tumor growth or survival in a breast cancer model, as compared to WT mice." (PMID 39336082, 2024). "Collectively, although 4T1 breast cancer transplantation strongly induced SAA1-2 in the liver, these acute phase proteins do not appear to be essential for cancer-dependent immune cell recruitments into the liver in the 4T1 model." (PMID 36817472, 2023). "Moreover, increased co-expression of SAA1 and FPR2 was observed in neutrophils isolated from breast cancer patients in comparison to those derived from healthy controls." (PMID 36817589, 2023). "Furthermore, to the lung-specific tumours, two hub genes were reported as a specific prognosis biomarker SAA1 and CCR5 with also T cell chemotaxis pathway This finding indicates that some pathways specifically determine the organ breast cancer metastasizes to." (PMID 35045088, 2022). "A previous study has demonstrated that breast cancer cells could release S100A4 to stimulate SAA1 and SAA3 expression via an autocrine manner, and that SAA1/SAA3 could promote metastasis of breast cancer cells." (PMID 31390756, 2019). "The lack of a similar outcome in the breast cancer model suggests that SAA1/2 may play different roles depending on the cancer type or tissue context." (PMID 39336082, 2024). "Thus, our results suggested that SAA1-2 proteins are not essential for liver inflammation observed in the 4T1 breast cancer model." (PMID 36817472, 2023). "We therefore investigated whether acute phase SAA1/2 isoforms could influence tumor growth, host survival, inflammation, and cellular programs in a breast cancer model by inducing tumors in genetically wild-type mice (WT), and mice lacking systemic SAA1/2 (SAADKO)." (PMID 39336082, 2024). "In the 4T1 breast cancer model, neutrophil blocking with anti-LY6G mAb with or without anti-SAA1 mAb slowed tumor growth." (PMID 36555469, 2022). "Notably, four hub genes (SAA1, CCR3, CCR5 and CXCL11) were unique among the breast cancer LM2 cell line; they were not identified among DEGs from the metastatic BrM2 cell line." (PMID 35045088, 2022).
pancreatic cancer (18 papers, 2019 to 2025). "Overexpression of SAA1 expression pancreatic cancer cells causes enhanced migration/ invasion capability, drug resistance, and EMT properties, while knockdown of SAA1 reverses these phenomena." (PMID 34884984, 2021). "In addition, the SAA1 gene encodes high-density lipoprotein-associated with inflammation, and high expression of SAA1 in pancreatic cancer predicts poor prognosis." (PMID 35432485, 2022). "In pancreatic cancer, SAA1 has been shown to promote progression through its involvement in inflammation." (PMID 40565234, 2025). "To elucidate the regulatory mechanism by which miR‐199a‐3p upregulates SAA1 expression in pancreatic cancer, we conducted TargetScan analysis to identify potential downstream targets of miR‐199a‐3p." (PMID 39431622, 2024). "In conclusion, our study highlights the role of CAAs in promoting pancreatic cancer progression through the secretion of miR‐199a‐3p‐enriched exosomes targeting the SOCS7/STAT3/SAA1 pathway." (PMID 39431622, 2024). "Previously, we found that CAA‐CM derived from mouse 3T3 adipocytes promotes the malignant transformation of pancreatic cancer cells via SAA1 upregulation." (PMID 39431622, 2024). "To further validate the influence of miR‐199a‐3p on SOCS7 and SAA1 expression in pancreatic cancer cells, we transfected three pancreatic cancer cell lines (Panc‐1, PK‐1, and PK‐45H cells) with a miR‐199a‐3p mimic." (PMID 39431622, 2024). "In the current study, we confirmed that CAA‐CM from human adipocytes also upregulated the expression of SAA1 in pancreatic cancer cells." (PMID 39431622, 2024). "Our previous research demonstrated that the conditioned medium from CAAs (CAA‐CM) enhances migration, invasion, and chemoresistance and promotes epithelial‐mesenchymal transition in pancreatic cancer cells by elevating SAA1 expression." (PMID 39431622, 2024). "miR‐199a‐3p in CAA‐derived exosomes contributes to the malignant transformation of pancreatic cancer via the SOCS7/STAT3/SAA1 pathway, suggesting its potential as a biomarker and therapeutic target for PDAC." (PMID 39431622, 2024). "In this study, we demonstrated that exosomal miR‐199a‐3p secreted from CAAs contributes to the malignant transformation of pancreatic cancer cells by promoting the expression of SAA1 via the miR‐199a‐3p/SOCS7/STAT3 pathway." (PMID 39431622, 2024). "Serum Amyloid A1 (SAA1), another protein induced in pancreatic cancer cells, attracts neutrophils to the tumor nest by interacting with TLR2 (Toll-Like Receptor 2)." (PMID 37835519, 2023). "It has recently been reported that SAA1 knockdown in pancreatic cancer cells led to enhanced migration/invasion, drug resistance, and EMT phenotype via NF‐κB activation." (PMID 37081987, 2023). "Here, we observed high SAA1 levels and a reduction of the APOA1-to-SAA1 plasma ratio in patients with pancreatic cancer." (PMID 35577388, 2022). "Moreover, secreted SAA1 can act on neighboring pancreatic cancer cells, promoting their metastatic potential and chemoresistance via NF‐κB activation." (PMID 39431622, 2024). "Subsequently, exosomal miR‐199a‐3p secreted from CAAs and taken up by surrounding pancreatic cancer cells suppressed SOCS7 expression, leading to STAT3 activation and increased SAA1 expression, ultimately resulting in a more aggressive phenotype in pancreatic cancer cells." (PMID 39431622, 2024). "In addition, the role of SAA1 in pancreatic cancer was demonstrated wherein the knockdown of SAA1 in a human pancreatic cell line (PANC-1) improved response to chemotherapy, reduced epithelial-to-mesenchymal transition and reduced invasive capacity." (PMID 36817589, 2023). "Interestingly, plasma samples from pancreatic-cancer patients displayed a significantly reduced APOA1-to-SAA1 ratio and a reduced cholesterol efflux capacity compared with healthy donors." (PMID 35577388, 2022).
pancreatic cancer (continued). "Transfection with miR‐199a‐3p increased the proliferation, invasion, migration, and drug resistance of pancreatic cancer cells by downregulating SOCS7, increasing STAT3 phosphorylation, and upregulating SAA1 expression." (PMID 39431622, 2024). "sEVs promote STAT3 expression and serum amyloid A1 (SAA1) and SAA2 secretion by transporting the pro-inflammatory, cytokine IL-6 secreted by the fibroblasts, from pancreatic tumors to the IL-6 receptor on liver cells." (PMID 34980146, 2022). "Hence, we focused on exosomal miRNAs that regulate SAA1 expression through crosstalk between CAA and pancreatic cancer cells in the tumor microenvironment." (PMID 39431622, 2024). "Interestingly, SAA1, an acute phase protein that associates with and potentially decreases the efflux capacity of HDL particles, was highly enriched in plasma samples of pancreatic-cancer patients, thereby reducing the APOA1-to-SAA1 ratio in those patients." (PMID 35577388, 2022). "Our notion that experimental conditions might influence the roles of SAA1-2 does not contradict the previous report showing the critical role of SAA proteins in recruiting neutrophils to the liver in the presence of pancreatic cancers." (PMID 36817472, 2023). "A study reported that simple blocking of serum amyloid A1 (SAA1), poor prognostic marker in pancreatic cancer cells, did not inhibit tumor growth and they verified two subtypes: saa3-competent and saa3-null CAFs, which showed pro-tumorigenic and anti-tumorigenic effect, respectively." (PMID 30680600, 2019).
Insulin resistance (17 papers, 2010 to 2026). Increased resistance towards insulin, that is, diminished effectiveness of insulin in reducing blood glucose levels. "PA-induced cell insulin resistance models were established in order to ascertain as to whether SAA1 was associated with the NF-κB pathway in PA-induced insulin resistance." (PMID 31060494, 2019). "In murine models, high-fat diet (HFD) feeding leads to early upregulation of Saa3 in adipose tissue, followed by increased hepatic expression of Saa1 and Saa2, in parallel with the development of insulin resistance and rising serum Saa levels." (PMID 41313351, 2026). "SAA is related to HFD-induced obesity, and SAA1 expression can promote liver insulin resistance and intrahepatic platelet aggregation aggravating liver inflammation." (PMID 39770043, 2024). "Palmitate (PA)-induced insulin resistance Huh7 cell models and high-fat diet (HFD)-induced mouse models were established to elucidate the effect of SAA1/Saa1 on insulin resistance." (PMID 31060494, 2019). "In the present study, we investigated the role of SAA1 in insulin resistance by establishing PA-induced cell insulin resistance models." (PMID 31060494, 2019). "Taken together, our key findings highlight a novel mechanism by which silencing of SAA1 hinders PA or HFD-induced insulin resistance through inhibition of the NF-κB pathway." (PMID 31060494, 2019). "In order to further investigate the effect of SAA1 on PA-induced insulin resistance, SAA1 was overexpressed or silenced in Huh7 cells." (PMID 31060494, 2019). "Accumulating reports have highlighted that serum amyloid A-1 (SAA1) is a potential candidate that is capable of attenuating insulin resistance." (PMID 31060494, 2019). "HFD-induced mice were employed to establish insulin resistant mouse models in order to elucidate the role of Saa1 in insulin resistance in vivo." (PMID 31060494, 2019). "The key findings from this study revealed that the inactivation of the NF-κB pathway and silencing of SAA1 exert a positive effect on insulin resistance through the enhancement of insulin sensitivity both in vitro and in vivo." (PMID 31060494, 2019). "Scheja and colleagues investigated this hypothesis and found that in insulin resistance prone mice that were fed a high-fat diet, liver SAA1 and SAA2 mRNA levels, and adipose tissue SAA3 mRNA levels were increased." (PMID 35883605, 2022). "However, during the current study, we found that SAA1 silencing resulted in the downregulation of the NF-κB pathway in insulin resistance, which was further reflected by reductions in p65 protein expression." (PMID 31060494, 2019). "Hence, we established PA- and high-fat diet (HFD)-induced insulin resistance cell and mouse models in order to investigate the effects of SAA1/Saa1 and the NF-κB pathway on insulin resistance." (PMID 31060494, 2019). "Saa1 was determined to be highly expressed in HFD-induced insulin resistance mouse models." (PMID 31060494, 2019). "C3, Saa1 and Saa3, which is regulated by S100a8, encode secretory proteins that can excrete from adipocytes into the local environment, leading to the enhanced inflammation in WAT and insulin resistance." (PMID 31614949, 2019). "Saa1, a marker of high fat diet induced hepatic insulin resistance, is suppressed by UAG." (PMID 20668691, 2010). "Subsequent work showed that in palmitate- or HFD-induced models, Saa1 upregulation inhibited IRS-1 signaling via NF-κB activation, contributing to insulin resistance." (PMID 41313351, 2026). "Studies suggest SAA1 has critical relationship with HDL-C level, can potentially alter lipid homeostasis, has regulatory function in cholesterol metabolism, and its suppression can help in high fat diet induced insulin resistance." (PMID 40473938, 2025).
Insulin resistance (continued). "However, more large scale studies are required in terms of collecting information on insulin resistance patients and dividing them into obese and non-obese groups to explore the difference of SAA1, the pathological and clinical features between the two groups." (PMID 31060494, 2019). "The initial findings of our study demonstrated that a decrease in the expression of SAA1 could improve glucose tolerance in mice on HFD; moreover, there exists a positive correlation between SAA1 and insulin resistance and that the silencing of SAA1 results in an increase in insulin sensitivity." (PMID 31060494, 2019). "In addition, recent work in which transgenic male mice have been engineered to express human SAA1 in intra-abdominal adipose tissue showed no negative effects on insulin resistance." (PMID 25251243, 2014).
atherosclerosis (16 papers, 2010 to 2024). A disease characterized by the build-up of fatty material and calcium deposition in the arterial wall resulting in partial or complete occlusion of the arterial lumen. "Our group has shown that repeated injections of adenoviral vector expressing human SAA1 in apoE−/− mice in the immune-tolerant recombination activating gene-1-deficient background increased atherosclerosis." (PMID 34944527, 2021). "Interestingly, Saa1 and Saa2, acute phase proteins proposed to play causal roles in atherosclerosis and AAAs, were two of the most highly downregulated proteins within AAAs from RXP470.1-treated Apoe−/− mice." (PMID 38891996, 2024). "This indicates that SAA1 is causal in plaque progression and thus leads to atherosclerosis." (PMID 23894396, 2013). "Lentiviral expression of murine SAA1 in atherosclerosis-prone ApoE-/- mice led to an elevation of Lp-PLA2 co-localizing with macrophages in atherosclerotic plaques." (PMID 36817589, 2023). "In fact, various studies have not only confirmed the important role of SAA1 in diseases related to the formation of atherosclerosis but also showed the potential role of SAA1 in atherosclerosis to varying degrees." (PMID 36158875, 2022). "Deficiency or suppression of all three acute phase SAAs: SAA1, SAA2.1, and SAA3 was necessary to significantly reduce atherosclerosis in apoE−/− mice." (PMID 36297390, 2022). "In particular, SAA1 has been shown to promote the formation of foam cells in vitro and atherosclerosis in vivo." (PMID 36158875, 2022). "The role of SAA1 in enhancing monocyte/platelet adhesion to endothelial cells was also proved, and these findings extended the regulatory role of SAA1 in promoting atherosclerosis." (PMID 36158875, 2022). "We also demonstrated that even a single injection of the adenoviral vector encoding SAA1, resulting in only a brief elevation of circulating SAA, was sufficient to increase atherosclerosis." (PMID 34944527, 2021). "Recently, SAA1 was also found to be associated mostly with high density lipoproteins (HDL), involving in lipid metabolism in atherosclerosis." (PMID 31216990, 2019). "A subsequent study in Apoe-deficient male mice also lacking Saa1 and Saa2 using Saa3 suppression with an anti-sense oligonucleotide showed significantly reduced atherosclerosis." (PMID 37396595, 2023). "SAA1 could promote atherosclerosis through enhancing endothelial cell activation, foam-cell formation, platelet aggregation, and monocyte/platelet adhesion to endothelial cells." (PMID 36158875, 2022). "Fourth, there may be clinical value in seeking new pharmacologic inhibitors against the functional activity of SAA1 to block the formation of atherosclerosis." (PMID 36158875, 2022). "Conclusively, it is speculated that SAA1 promotes atherosclerosis through enhancing endothelial cell activation, platelet aggregation, foam-cell formation, and monocyte/platelet adhesion to endothelial cells." (PMID 36158875, 2022). "Here, based on in vitro evidence that SAA1 promotes atherosclerosis, we further confirm that such function of SAA1 may depend on activation of the TLR4-related NF-κB signaling pathway." (PMID 36158875, 2022). "Therefore, SAA1 is candidates for atherosclerosis and cerebral infarction." (PMID 23987125, 2013). "As another aspect, proteomics research found elevated levels of SAA1 in HDL of patients with CKF, indicating a potential relation with atherosclerosis." (PMID 37510279, 2023). "Third, there are many potential receptors for SAA1, and our study clarified only the potential role of TLR4 signaling in SAA1-induced atherosclerosis; whether other receptors also play corresponding functions needs to be further explored." (PMID 36158875, 2022).